BSCL2 (BSCL2 lipid droplet biogenesis associated, seipin)
Diseases named in the same sentence as BSCL2 in open-access papers (continued):
Sharing a sentence is not in itself a finding about the gene and the disease.
generalized lipodystrophy (18 papers, 2013 to 2026). Almost complete absence of subcutaneous and/or visceral adipose tissue. "For instance, delivery of human BSCL2 gene via adeno-associated virus in a pre-clinical mouse model of congenital generalized lipodystrophy has shown promising results." (PMID 39872985, 2025). "Most recently, a case series describing patients with a form of congenital generalized lipodystrophy presented with progressive myoclonus epilepsy was reported and attributed to novel mutations in the BSCL2 (Seipin) gene." (PMID 39319257, 2024). "In recent years, other variants in BSCL2 associated with generalized lipodystrophy and progressive epileptic encephalopathy have been reported." (PMID 33916074, 2021). "A homozygous and truncating mutation was identified in the BSCL2 gene suggesting congenital generalized lipodystrophy." (PMID 24961962, 2014). "Mutation identified here in BSCL2 gene causing congenital generalized lipodystrophy is the first report in Pakistani population." (PMID 23659685, 2013). "To note, cardiac MRI in patients with congenital generalized lipodystrophy due to BSCL1 or BSCL2 pathogenic variants also show a concentric LV hypertrophy, independent of blood pressure, which could be due to increased myocardial triglyceride content." (PMID 32245113, 2020). "While pathogenic mutations in BSCL2/Seipin cause congenital generalized lipodystrophy, the underlying mechanism is largely unknown." (PMID 23520483, 2013). "Individuals reported in the studies included 90 with partial lipodystrophy (72 due to LMNA mutation and 15 due to PPARG mutation), 42 with generalized lipodystrophy (21 AGPAT2, 21 BSCL2, 2 LMNA), and 19 with IR due to INSR mutation(s)." (PMID 37794082, 2023). "The main known candidate genes associated with congenital generalized lipodystrophy, i.e. BSCL1/AGPAT2, BSCL2/seipin, BSCL3/caveolin-1 and BSCL4/PRTF were analyzed." (PMID 23919306, 2013). "In the case of genes causing generalized lipodystrophy, this may reflect the fact that while disruption of BSCL2 or AGPAT2 leads principally to a lack of adipose tissue, PTRF and CAV1 mutations cause a more complex phenotype in affected patients." (PMID 30940487, 2019).
congenital generalized lipodystrophy type 2 (17 papers, 2011 to 2026). Any congenital generalized lipodystrophy in which the cause of the disease is a mutation in the BSCL2 gene. "Congenital generalized lipodystrophy type 2 is a rare autosomal recessive disorder caused by mutation in the BSCL2 gene." (PMID 42082457, 2026). "Mutations in BSCL2 are associated with congenital generalized lipodystrophy type 2, as well as neurodegenerative axonopathies such as hereditary spastic paraplegia and distal hereditary motor neuropathy." (PMID 40735840, 2025). "Congenital generalized lipodystrophy type 2 (CGL2) is a very rare autosomal recessive disorder caused by pathogenic variants in the BSCL2 gene." (PMID 41465464, 2025). "Uniquely, certain variants in BSCL2 can cause both generalized congenital lipodystrophy type 2, upper and/or lower motor neuron diseases, or progressive encephalopathy, with a poor prognosis during childhood." (PMID 33916074, 2021). "Mutations in the gene known as BSCL2 are involved in type 2-Berardinelli-Seip congenital lipodystrophy." (PMID 28986436, 2017). "The BSCL2 gene is associated with congenital generalized lipodystrophy type 2 (CGL2) and, indeed, clinical re-evaluation of our patients confirmed characteristic clinical features of the disease in all three affected members." (PMID 24961962, 2014). "BSCL2 mutations are associated with Berardinelli-Seip congenital lipodystrophy and a clinical re-evaluation of affected individuals confirmed the diagnosis." (PMID 24961962, 2014). "Dysfunctional seipin, resulting from mutations in the BSCL2 gene, causes congenital generalized lipodystrophy type 2, a severe inherited disorder characterized by near-complete loss of adipose tissue, likely due to impaired mesenchymal stem cell differentiation into preadipocytes." (PMID 41226321, 2025). "Using whole exome sequencing (WES), we identified a homozygous mutation in the acceptor splice site of intron 5 of the BSCL2 gene previously associated to congenital generalized lipodystrophy type 2 (CGL2)." (PMID 24961962, 2014). "Seipin (BSCL2/SPG17) is a key factor in lipid droplet (LD) biology, and its dysfunction results in severe pathologies, including the fat storage disease Berardinelli-Seip congenital lipodystrophy type 2, as well as several neurological seipinopathies." (PMID 30901948, 2019). "Conditions associated with variants in the BSCL2/seipin gene include progressive encephalopathy with/without lipodystrophy (PELD), also called Celia’s encephalopathy (MIM#615924) and congenital general lipodystrophy type 2 (CGL2)." (PMID 33099310, 2020).
Hepatic steatosis (12 papers, 2016 to 2025). Steatosis is a term used to denote lipid accumulation within hepatocytes. "Individuals affected by mutations in BSCL2 develop severe metabolic complications, including hepatic steatosis and diabetes." (PMID 36830428, 2023). "Germline Bscl2 loss in mice and BSCL2 disruption in humans causes severe hepatic steatosis, and the encoded protein, seipin, has acknowledged roles in lipid accumulation." (PMID 31848133, 2020). "Severe hepatic steatosis is a striking feature found in all Bscl2 global knockout mice and in patients that suffer from CGL24." (PMID 30552349, 2018). "However, a recent study highlighted that AAV-mediated overexpression of Bscl2 in the liver alleviated high-fat diet-induced hepatic steatosis in WT mice, potentially indicating beneficial liver-mediated effects." (PMID 39069561, 2024). "Together, these reveal that hepatic deficiency of seipin does not appear to be responsible for significant increases in hepatocyte lipid content or the severe hepatic steatosis that is observed in global Bscl2 knockout mouse models or patients suffering from CGL2." (PMID 31848133, 2020). "Loss of hepatic BSCL2 is therefore unlikely to contribute significantly to the development of hepatic steatosis or metabolic dysfunction in this form of CGL." (PMID 31848133, 2020). "Therefore, it would appear that Bscl2 loss in hepatocytes does not play a significant role in the development of hepatic steatosis or glucose intolerance in seipin-deficient states, even on a background of generalised lipodystrophy." (PMID 31848133, 2020). "Our in vivo findings are in keeping with previously published data in which liver-specific Bscl2 knockout mice did not develop glucose intolerance or hepatic steatosis, even when challenged with a high-fat diet." (PMID 31848133, 2020). "Bscl2 ablation specifically in the liver does not appear to lead to hepatic steatosis or diabetes, even when the mice are challenged with a high-fat diet." (PMID 29459250, 2018). "However, the increase in liver TG levels in Ad-B2(−/−) mice was much less severe than that seen in previously reported Bscl2-null mice, consistent with the absence of overt liver steatosis in our model." (PMID 29459250, 2018).
diabetes (9 papers, 2015 to 2024). "BSCL2 encodes seipin, a transmembrane endoplasmic reticulum protein associated with lipodystrophy and severe metabolic complications, including diabetes and hepatic steatosis." (PMID 36830428, 2023). "In summary, patients with BSCL2 mutations show earlier age of onset of diabetes mellitus, higher risk to suffer from premature death and mental retardation and are more severe than patients with AGPAT2 mutations." (PMID 32349771, 2020). "All patients (n = 12) for which we performed genotyping had the 325dupA variant in the BSCL2 gene (rs786205071) and all but one patient at the time of death had diabetes." (PMID 29883474, 2018). "According to the report by Agarwal and his colleagues, patients with BSCL2 mutation had an onset of diabetes at a median age of 10 years." (PMID 27612026, 2017). "Our case report analyzes the causes of early onset diabetes may relate with the locus of BSCL2 gene mutations and infection induction." (PMID 35351089, 2022). "Patients with CGL and BSCL2 variants have lower leptin levels and an earlier onset of diabetes than those without these variants." (PMID 29704234, 2019).
neuropathies (9 papers, 2012 to 2022). "Neuropathy-causing BSCL2 mutations have been shown to affect the glycosylation sites of BSCL2 and lead to the accumulation of the unfolded protein in the ER." (PMID 28553203, 2017). "Following the BSCL2 p.N88S, p.S90L and p.S90W mutations, the p.R96H mutation is the fourth BSCL2 mutation identified to cause inherited neuropathy." (PMID 26815532, 2016). "This point is further supported by two recent studies which utilized whole exome sequencing to investigate the genetic cause of inherited neuropathies with earlier unsuccessful candidate gene testing and both identified mutations in BSCL2 in their cases." (PMID 26815532, 2016). "Our study demonstrated that the frequency of BSCL2 mutations in Taiwanese patients with inherited neuropathy is low (0.57%; 2/348)." (PMID 26815532, 2016). "The variable features of neuropathies are mostly associated with heterozygous mutations in BSCL2 dHMN, Charcot-Marie-Tooth (CMT) and Silver syndromes." (PMID 23659685, 2013). "BSCL2 mutations account for a small number of patients with inherited neuropathies in Taiwan." (PMID 26815532, 2016). "Although all CMT neuropathies cause length-dependent damage, the upper limbs are frequently clinically involved in CMT1A or CMT1X and predominantly in some forms, such as neuropathies caused by GARS and BSCL2 pathogenic variants." (PMID 35330153, 2022). "Silver syndrome, which is a complicated SPG, is a good example of a disease that is caused by a BSCL2 mutation that can present with neurologic features on a spectrum between SPG and Charcot–Marie–Tooth (CMT) neuropathy." (PMID 31475473, 2019). "Clinical neuropathy and cognitive deficits are associated with CGL2 and mutations in seipin (BSCL2), and are rare but not unknown for CGL3 and CGL4 syndromes [associated with caveolin-1 (CAV1) and cavin (RNA polymerase 1 and transcript release factor: PTRF) gene mutations, respectively]." (PMID 30563316, 2019).
distal hereditary motor neuropathy (6 papers, 2014 to 2026). "Nevertheless, it was identified that mutations in BSCL2 are associated with distal hereditary motor neuropathy (dHMN) and with Charcot–Marie–Tooth disease type 2 (CMT2) in a Taiwanese cohort." (PMID 36830428, 2023). "Finally mutations in BSCL2 (Bernardinelli-Seip Congenital Lipodystrophy Type 2) also known as seipin cause a distal hereditary motor neuronopathy (HMN5C) which can present with features of axonal CMT269." (PMID 35662277, 2022).
hypertriglyceridemia (5 papers, 2018 to 2024). A laboratory test result indicating elevated triglyceride concentration in the blood. "Of note, SKO mice are hyperglycaemic but do not display the hypertriglyceridemia observed in BSCL2-deficient patients." (PMID 33498782, 2021). "In this case, physical examination was puzzling, but 2 clinical features set apart the infant bearing an BSCL2 variant from the INSR group: lack of intrauterine growth restriction and hypertriglyceridemia." (PMID 38408297, 2024).
hypertrophic cardiomyopathy (5 papers, 2018 to 2022). A condition in which the myocardium is hypertrophied without an obvious cause. "Different from hypertrophic cardiomyopathy in Bscl2−/− mice, mice with cardiac‐specific deletion of Bscl2 developed systolic dysfunction with dilation." (PMID 35384404, 2022). "Hypertrophic cardiomyopathy and cardiac dysfunction in Bscl2 knockout mice appears to be due to glucotoxicity." (PMID 29459250, 2018). "Furthermore, global lipodystrophic Bscl2−/−mice exhibit hypertrophic cardiomyopathy with reduced cardiac steatosis, and mice with cardiac-specific deletion of Bscl2 developed systolic dysfunction with dilation, through excessive lipid catabolism." (PMID 36510129, 2022).
motor neuron disease (5 papers, 2015 to 2026). "Both CGL2 and PELD are inherited as autosomal recessive, whereas BSCL2-associated motor neuron diseases are almost all autosomal dominant." (PMID 35740965, 2022). "Therefore, we call “seipinopathies termed by Ito” other than CGL2 and PELD as “BSCL2-associated motor neuron diseases” as per a dyadic nomenclature in this review." (PMID 35740965, 2022). "Because the first two seipinopathy-related mutations, BSCL2 p.N88S and p.S90L, were originally identified in patients with dHMN or Silver syndrome, seipinopathy is commonly recognized as a spectrum of motor neuron disorders presenting with variable combination of upper and lower motor neuron signs." (PMID 26815532, 2016). "Furthermore, a single BSCL2 variant including p.N88T, p.S141A, or p.R96H may also result in one patient with motor neuron diseases, respectively." (PMID 35740965, 2022). "Single heterozygous, compound heterozygous, or homozygous missense mutation (N88S or S90L) in BSCL2 causes a broad spectrum of motor neuron diseases, not CGL2." (PMID 35740965, 2022). "However, following the terminology used for diseases caused by lamin A/C (LMNA) gene mutations, all diseases caused by BSCL2 mutations (CGL2, PELD, and BSCL2-associated motor neuron diseases) should be called “seipinopathies”." (PMID 35740965, 2022).
steatosis (5 papers, 2021 to 2026). Increased lipid within the cytoplasm of cells. "Abnormal expression of the BSCL2 gene is associated with the occurrence and development of steatosis." (PMID 41149615, 2025).
cardiomyopathy (4 papers, 2015 to 2024). A disease of the heart muscle or myocardium proper. "This, together with lipid accumulation implicates the occurrence of “lipotoxic” cardiomyopathy in Atp6v0d1AKO mice, which is in contrast to Bscl2-/- cardiomyopathy mainly caused by hyperglycemia and glucotoxicity." (PMID 38505620, 2024). "Yet, loss of BSCL2 specifically in the myocardium also leads to the onset of cardiomyopathy 41, adding the complexity of this model as whether dysfunctional AT or altered cardiac functions as the direct cause for cardiomyopathy." (PMID 38505620, 2024). "Data from the literature indicate that BSCL2 patients have an increased risk of cardiomyopathy and intellectual impairment compared with BSCL1 patients, suggesting that seipin, the protein encoded by the BSCL2 gene, is involved in the regulation of neuronal functions." (PMID 29046728, 2017). "First, lipid deposition in the heart, a pathological change that is widely observed in patients with lipodystrophy cardiomyopathy, is evident in Atp6v0d1AKO mice, whereas Bscl2-/- cardiomyopathy is characterized by reduced lipid accumulation." (PMID 38505620, 2024). "This is particularly interesting, as BSCL2 patients frequently suffer from cardiomyopathy not seen with AGPAT2 deficiency in BSCL1 patients." (PMID 25737955, 2015).
distal hereditary motor neuropathy type V (4 papers, 2014 to 2021). "BSCL2 mutations can also cause a range of phenotypes with lower motor neurone involvement including multifocal motor neuropathy with conduction block, Charcot-Marie-Tooth neuropathy type 2 and distal hereditary motor neuropathy type V." (PMID 33646413, 2021).
Hyperglycemia (4 papers, 2018 to 2024). An increased concentration of glucose in the blood. "Using the SKO pre-clinical mouse model of CGL2, we demonstrate that a single injection with AAV bearing human BSCL2 reversed hyperglycemia, hepatomegaly, and IR." (PMID 36320417, 2022).
Spastic paraplegia (4 papers, 2016 to 2021). Complete loss of the ability to move the lower limbs accompanied by spasticity of the lower limbs. "dHMN can also overlap with spastic paraplegia (e.g., BSCL2)." (PMID 34438578, 2021).
Cognitive impairment (3 papers, 2018 to 2024). Abnormal cognition is characterized by deficits in thinking, reasoning, or remembering. "Concerning genetic consequences, mutations in the AGPAT2 gene are associated with the occurrence of bone cysts, while mutations in the BSCL2 gene are associated with cognitive deficits and a higher incidence of premature death." (PMID 29864145, 2018). "Lack of Seipin gene, Bscl2, leads to not only severe lipid metabolic disorders but also cognitive impairments and motor disabilities." (PMID 38773070, 2024).
Encephalopathy (2 papers, 2019). Encephalopathy is a term that means brain disease, damage, or malfunction. "Noteworthy among these links is educational attainment-associated BSCL2, known to carry mutations leading to a Mendelian form of encephalopathy." (PMID 31341166, 2019). "In particular, some variants in BSCL2 are associated with lethal encephalopathy in early childhood." (PMID 29704234, 2019).
glioblastoma (2 papers, 2022 to 2024). The most malignant astrocytic tumor (WHO grade IV). "In glioblastoma patients and glioblastoma cell lines, the expression of BSCL2 is increased." (PMID 35740965, 2022). "in 2021 found that the prognosis of glioblastoma (GBM) can be determined by seven differentially expressed genes (DEGs) 47, namely CLEC5A, HOXC6, HOXA5, CCL2, GPRASP1, BSCL2, and PTX3." (PMID 39132508, 2024).
Glucose intolerance (2 papers, 2018 to 2020). Glucose intolerance (GI) can be defined as dysglycemia that comprises both prediabetes and diabetes. "Likewise, mice lacking Bscl2 in all tissues have dramatically reduced adipose mass, glucose intolerance and hyperinsulinaemia." (PMID 30552349, 2018).
hereditary spastic paraplegia (2 papers, 2017 to 2025). Hereditary spastic paraplegias (HSP) comprise a genetically and clinically heterogeneous group of neurodegenerative disorders characterized by progressive spasticity and hyperreflexia of the lower limbs. "Of note, there are nine genes among these targets that when mutated are known causes for inherited peripheral neuropathies (IPN) and hereditary spastic paraplegia (HSP) (Inf2, Sox10, Wnk1, Med25, Fa2h, Bscl2, Slc12a6, Kif1a and Kif5a)." (PMID 28077174, 2017). "Furthermore, transcripts of disease-associated genes, such as BSCL2-206, REEP1-201, UCHL1-207/209 and KIF5A-202, all associated with hereditary spastic paraplegia (HSP), were significantly differentially expressed." (PMID 40735840, 2025).
hyperinsulinemia (2 papers, 2014 to 2020). An increased concentration of insulin in the blood. "A causal relationship between hyperinsulinemia and CH in patients with BSCL2 mutations is suggested in two patients in whom CH improved or even regressed after correction of the hyperinsulinism." (PMID 31840185, 2020).
intellectual disabilities (2 papers, 2021 to 2024). "Unlike AGPAT2 mutations, which primarily affect adipose tissue, BSCL2 mutations can impact various tissues, potentially contributing to intellectual disabilities due to Seipin's expression in the brain." (PMID 39131003, 2024). "Moderate intellectual disability can be observed in type 2 Congenital Generalized Lipoatrophy (CGL) due to BSCL2 pathogenic variants encoding seipin." (PMID 35046902, 2021).
Obesity (2 papers, 2014 to 2023). Accumulation of substantial excess body fat. "BSCL2 was investigated regarding processes related to obesity/fatness, which is defined as excessive accumulation of triacylglycerol in WAT, specifically in lipid droplets." (PMID 36830428, 2023).
Progressive myoclonic epilepsy (2 papers, 2019 to 2020). "PELD is associated with BSCL2 variants that cause skipping of exon 7 and is characterized by the development of progressive myoclonic epilepsy (PME) at a young age and severe progressive neurological impairment, which is rapidly fatal in many, but not all, cases." (PMID 33099310, 2020).
Silver syndrome (2 papers, 2019 to 2021). "For a robust genetic diagnosis of CMT2 as well as CMT2 differentiation from Silver syndrome and dHMNV, seipin/BSCL2 mutation screening seems to be important, particularly in patients with apparently upper motor neuron and lower motor neuron involvement." (PMID 32489946, 2019).